TREM2 (triggering receptor expressed on myeloid cells 2)
Diseases named in the same sentence as TREM2 in open-access papers (continued):
Sharing a sentence is not in itself a finding about the gene and the disease.
Alzheimer disease (continued). "This would be in keeping with a report that TREM2 variant carriers are more likely to develop an atypical variant of Alzheimer’s disease." (PMID 37990275, 2023). "One of the highest impact risk gene variants for Alzheimer’s disease is in the gene for TREM2 (triggering receptor expressed on myeloid cells 2)." (PMID 37990275, 2023). "Trem2 is also known to regulate the expression of genes associated with cell damage response, lysosome and phagosome function, Alzheimer's disease, and oxidative phosphorylation." (PMID 37246643, 2023). "Heterozygous rare variants in TREM2 increase the risk for neurodegenerative diseases, such as Alzheimer’s disease, Parkinson’s disease and amyotrophic lateral sclerosis." (PMID 36977680, 2023). "The rare TREM2 rs75932628 non-synonymous coding variant (p.R47H) has a similar effect size to APOEε4, with a 2- to 3-fold increased risk of Alzheimer’s disease in heterozygous carriers." (PMID 37990275, 2023). "We discussed a potential application for treating Alzheimer’s disease (AD) by replacing microglia deficient in TREM2, which is one of the major risk factors in sporadic AD, with TREM2-normal microglia." (PMID 38131301, 2023). "The rare p.H157Y variant of TREM2 (Triggering Receptor Expressed on Myeloid Cells 2) was found to increase Alzheimer’s disease (AD) risk." (PMID 36721205, 2023). "TREM2 expression has been shown to be upregulated in microglia that associate with amyloid plaques in Alzheimer's disease (AD)." (PMID 36480007, 2023). "Pathway enrichment analysis based on Enrichr showed that Trem2-KO responsive genes were enriched with genes associated with interleukin-2 signaling pathway, lysosome, and Alzheimer's disease." (PMID 37246643, 2023). "Mutations in TREM2 are strongly linked with a higher risk of developing neurodegenerative diseases, including Alzheimer’s disease." (PMID 37942087, 2023). "Mutations of TREM2 contribute to late-onset Alzheimer’s disease because these variants disturb TREM2 signaling and its functions." (PMID 37444065, 2023). "The TREM2 R47H variant is one of the strongest genetic risk factors for late-onset Alzheimer’s Disease (AD)." (PMID 36803190, 2023). "Heterozygous rare variants in TREM2 are associated with increased risk for neurodegenerative diseases (NDDs), including Alzheimer’s disease (AD), Parkinson’s disease (PD), frontotemporal dementia (FTD) and amyotrophic lateral sclerosis (ALS)." (PMID 37240695, 2023). "More recently, missense heterozygous variants in TREM2 have been implicated in risk for late-onset Alzheimer’s disease (AD) and frontotemporal dementia." (PMID 37115208, 2023). "Triggering receptor on myeloid cells 2 (TREM2) is an innate immune receptor, upregulated on the surface of microglia associated with amyloid plaques in Alzheimer's disease (AD)." (PMID 36480007, 2023). "The CD300f immune receptor shares many characteristics with TREM2, a key immune receptor for determining the phenotype of microglia and macrophages, and one of the main risk factor genes for the development of Alzheimer’s Disease (AD) and Nasu Hakola Disease1." (PMID 37798310, 2023). "In Alzheimer’s disease, a decrease in TREM2 accelerates the process of ageing and neural loss, finally, it reduces microglial activity and leads to neuroinflammation." (PMID 36463233, 2022). "Possessing some rarely occurring alleles of TREM2 encoding gene is a risk factor of late-onset Alzheimer’s disease." (PMID 36045741, 2022). "TREM2 (a risk gene of Alzheimer’s disease related to microglial phagocytosis) KO mice displayed autistic-like behaviors and reduced microglial synaptic elimination." (PMID 35693812, 2022). "For example, expression of triggering receptor expressed on myeloid cells-2 (TREM2) is important for the disease-associated activation of the microglia in a mouse model of Alzheimer’s disease-like pathology." (PMID 35875357, 2022).
Alzheimer disease (continued). "Heterozygous rare variants in TREM2 have been reported to increase the risk of Alzheimer’s disease (AD) and identified in other neurodegenerative disorders such as frontotemporal dementia and Parkinson’s disease as well." (PMID 36389767, 2022). "It has been found that the abnormal TREM2 expression was associated with the development and progression of neurological pathologies, such as Alzheimer's disease." (PMID 36438899, 2022). "Trem2 enhances the phagocytosis function of microglia and suppress neuroinflammation; in humans, TREM2 loss-of-function variants are associated with Alzheimer’s disease." (PMID 35967299, 2022). "Previous studies have shown that TREM2 coding variations enhance the risk of Alzheimer’s disease and other neurodegenerative diseases." (PMID 36713360, 2022). "Microglia in the brain express TREM2 and mutations of TREM2 impact its ability to bind ligands, diminish microglial activation, and accelerate progression of Alzheimer’s Disease." (PMID 36119485, 2022). "Consistent with the reduced risk of Alzheimer’s disease in ε2 carriers, microglia incubated with apoE2 showed lower TREM2 activation compared to apoE3-incubated microglia." (PMID 36077289, 2022). "Although TREM2 has been implicated in a wide array of immune functions especially related to chronic and degenerative diseases, such as Alzheimer disease and dementia, various aspects of its signalling in other biological contexts remain poorly understood." (PMID 35723745, 2022). "Genetic variants in TREM2, a microglia-related gene, are well-known risk factors for Alzheimer’s disease (AD)." (PMID 35887031, 2022). "TREM2 mutations are risk factor for sporadic Alzheimer’s disease, and transgenic TREM2 deficiency in an AD murine model accelerates amyloid plaque deposition and neuron loss." (PMID 35663580, 2022). "Previous studies had confirmed that TREM2 mutations increased the risk of Alzheimer's disease (AD), whereas the association of TREM2 mutations with PD remains controversial." (PMID 35783125, 2022). "Other TREM-2 variants associated with the risk of Alzheimer’s disease have been identified and include rs72824905, rs616338, and rs143332484." (PMID 33578866, 2021). "Heterozygous mutations in TREM2, such as the R47Hhet mutation, are associated with Alzheimer’s disease, whilst homozygous missense TREM2 mutations such as T66M cause Nasu-Hakola disease, a rare early-onset dementia with bone cysts." (PMID 34704019, 2021). "Trem2 mutations have been reported to be involved in the development of various neurodegenerative diseases, such as Nasu‐Hakola disease, Alzheimer’s disease (AD), Parkinson’s disease (PD), and amyotrophic lateral sclerosis (ALS)." (PMID 33583110, 2021). "Genome sequencing of patients with Alzheimer’s disease and Nasu–Hokola disease has correlated Trem2 mutations with microglial disorders and disease progression." (PMID 34838047, 2021). "Homologous mutations in TREM-2 genes have resulted in several genetic variants that have been associated with an increased risk of developing Alzheimer’s disease and other neurodegenerative diseases." (PMID 33578866, 2021). "Mutations in TREM2, a receptor expressed by microglia in the brain, are associated with an increased risk of neurodegeneration, including Alzheimer's disease." (PMID 34233201, 2021). "TREM2 is a risk factor for Alzheimer’s disease and is believed to modulate the behavior of microglia to exacerbate the inflammatory response." (PMID 33782087, 2021). "Several genetic studies have identified a rare variant of triggering receptor expressed on myeloid cells 2 (TREM2) as a risk factor for Alzheimer’s disease (AD)." (PMID 34064330, 2021).
Alzheimer disease (continued). "We investigated the influence of the TREM2 Alzheimer’s disease risk variant, R47Hhet, on the microglial exosomal proteome consisting of 3019 proteins secreted from human iPS-derived microglia (iPS-Mg)." (PMID 34831089, 2021). "Recently, TREM2 expression has also been identified as a risk factor for late-onset dementia and Alzheimer’s disease." (PMID 33980160, 2021). "TREM2 signalling transduction has a central role in promoting microglial activation and variants in TREM2 have been linked to different types of neurological diseases, including multiple sclerosis, Parkinson’s and Alzheimer’s diseases." (PMID 34113350, 2021). "For further characterisation of the microglial response, the gene expression levels of the Alzheimer’s disease-associated microglial gene Trem2 were examined." (PMID 34266459, 2021). "Single-nucleotide polymorphisms, including the TREM2 R47H variant, increase the risk of dementia, including frontotemporal lobar degeneration, Parkinson’s disease, Alzheimer’s disease, and amyotrophic lateral sclerosis." (PMID 33863908, 2021). "Ligands for TREM2 include lipids and bacterial components, including the Alzheimer's disease-associated ApoE and Aβ oligomers." (PMID 34282843, 2021). "Rare sequence variants in the microglial cell surface receptor TREM2 have been shown to increase the risk for Alzheimer’s disease (AD)." (PMID 33839686, 2021). "Genetic polymorphisms in TREM2 are associated with an increased risk for neurodegenerative disease, most notably Alzheimer’s disease." (PMID 34751640, 2021). "The R47H variant of the microglial membrane receptor TREM2 is linked to increased risk of late onset Alzheimer’s disease." (PMID 34172778, 2021). "Variants in the Trem2 locus are associated with early-onset Alzheimer’s disease in humans, related to a reduced clearance of extracellular amyloid β–containing plaques due to an impaired function of microglia within the brain." (PMID 34851663, 2021). "TREM2 is among the most well-known Alzheimer’s disease (AD) risk genes; however, the functional roles of its AD-associated variants remain to be elucidated, and most known risk alleles are low-frequency variants whose investigation is challenging." (PMID 34576031, 2021). "Genetic variants and mutations in triggering receptor expressed in myeloid cells (TREM2) are associated with premature and late onset Alzheimer’s disease (AD)." (PMID 33422057, 2021). "Loss‐of‐function variants of triggering receptor expressed on myeloid cells 2 (TREM2) increase the risk of developing Alzheimer's disease (AD)." (PMID 34523252, 2021). "Genome-wide association studies (GWAS) have identified immune-related genes as risk factors for Alzheimer’s disease (AD), including TREM2 and CD33, frequently passing a stringent false-discovery rate." (PMID 34208838, 2021). "Heterozygous variants in TREM2 are known to be a risk factor for Alzheimer’s disease and levels of the TREM2 protein have been shown to be abnormal in FTD." (PMID 33210084, 2020). "The discovery of TREM2 as a myeloid-specific Alzheimer’s disease (AD) risk gene has accelerated research into the role of microglia in AD." (PMID 33097708, 2020). "SIGNIFICANCE STATEMENT Genetic studies indicate that TREM2 gene mutations confer increased Alzheimer's disease (AD) risk." (PMID 31980586, 2020). "Recently, the critical roles played by genetic variants of TREM2 (Triggering Receptor Expressed on Myeloid cells 2) in Alzheimer’s disease have been aggressively highlighted." (PMID 32107424, 2020). "Triggering receptor expressed on myeloid cells 2 TREM2 was identified as a risk factor for late onset Alzheimer's disease (AD)." (PMID 32267026, 2020). "Individuals with the rare R47H variant of TREM2 have substantial risk of developing late onset Alzheimer’s disease (AD)." (PMID 33115519, 2020). "TREM2 variants are associated with Alzheimer disease and soluble TREM2 (sTREM2) enhances microglial uptake and degradation of Amyloid beta." (PMID 32731618, 2020).
Alzheimer disease (continued). "To study the mechanisms by which the p.R47H variant of the microglia gene and Alzheimer’s disease (AD) risk factor TREM2 increases dementia risk, we created Trem2R47H KI rats." (PMID 32579116, 2020). "Mutations in TREM2 alter risk for Alzheimer’s disease, though the mechanisms underlying risk in human cells are unclear." (PMID 33097708, 2020). "We show that these TREM2 variant iPSC‐microglia, including the Alzheimer's disease R47H risk variant, exhibit significant metabolic deficits including a reduced mitochondrial respiratory capacity and an inability to perform a glycolytic immunometabolic switch." (PMID 31907987, 2020). "Sequence variants of the microglial expressed TREM2 (triggering receptor expressed on myeloid cells 2) are a major risk factor for late onset Alzheimer's disease." (PMID 32830336, 2020). "TREM2 is a microglial cell surface receptor, with risk mutations linked to Alzheimer’s disease (AD), including R47H." (PMID 33198789, 2020). "For instance, TREM2 has been deeply involved in the recognition of beta amyloid extracellular deposits in the context of Alzheimer's disease (AD), and is one of the main genetic risk factors for its development." (PMID 32292406, 2020). "This CD33 isoform counteracts the inhibitory effect of CD33 on TREM2 in microglia and would ultimately reduce amyloid deposition and thus exert a moderate protective effect on Alzheimer’s disease and likely SVID susceptibility." (PMID 32345996, 2020). "Genome-wide association studies have reported that, amongst other microglial genes, variants in TREM2 can profoundly increase the incidence of developing Alzheimer’s disease (AD)." (PMID 32959884, 2020). "The R47H variant of the Triggering-Receptor-Expressed on Myeloid cells 2 (TREM2) increases the risk of Alzheimer’s disease (AD)." (PMID 32139718, 2020). "The effects of genetic variants on TREM2 loss of function is crucial to understanding its involvement in late-onset Alzheimer’s disease (AD)." (PMID 32107424, 2020). "The rare R47H variant within triggering receptor expressed on myeloid cells 2 (TREM2) has been shown to increase the risk for developing Alzheimer’s disease (AD) 2–3-fold." (PMID 32630447, 2020). "Recent genome-wide association studies have identified several Alzheimer’s disease (AD)-associated risk loci in genes selectively or preferentially expressed in microglia (e.g. TREM2, ABI3, PLCG2)." (PMID 32917267, 2020). "Here we sought to identify genetic associations between POAG and variants in APOE and TREM2, genes associated with Alzheimer disease (AD) that critically regulate microglial neurodegeneration-associated molecular signature." (PMID 32614373, 2020). "Homozygous TREM2 mutations cause early onset progressive presenile dementia while heterozygous, point mutations triple the risk of Alzheimer’s disease (AD)." (PMID 32795308, 2020). "In contrast, two confirmed Alzheimer’s disease (AD) risk-modifying mutations of TREM2, R47H and R62H, occur within the ligand-binding domain of the protein and permit maturation and cell surface expression." (PMID 33198789, 2020). "In this review we discuss our current knowledge of the risk genes APOE4, BIN1, CD2AP, PICALM, PLD3 and TREM2 and their impact on endolysosomal (dys)regulations in the light of late-onset Alzheimer’s disease pathology." (PMID 31159836, 2019). "Triggering receptor expressed on myeloid cells 2 (TREM2) is a microglial surface receptor genetically linked to the risk for Alzheimer’s disease (AD)." (PMID 30911003, 2019). "TREM2 plays a protective role in mouse models of Alzheimer disease, and TREM2 variants are associated with an increased risk of Alzheimer disease." (PMID 31614590, 2019). "Genome-Wide Association Studies (GWAS) for late-onset Alzheimer’s disease (LOAD) identified the TREM2 missense variant R47H, which was also associated with impaired microglia function." (PMID 31614849, 2019).
Alzheimer disease (continued). "TREM2 is a genetic risk factor for Alzheimer’s disease, and soluble TREM2 (sTREM2) in the CSF correlates with AD progression." (PMID 30911003, 2019). "Within our mouse innate immune network, we first confirmed the significance of several members of the network that were orthologues of established Alzheimer’s disease loci variants using the gene-level P-values, including genes such as Trem2 and Abi3." (PMID 32274467, 2019). "Several genetic variants of the Triggering Receptor Expressed on Myeloid Cells-2 (TREM2) have been shown to increase the risk of developing Alzheimer’s disease (AD) supporting a role of microglia and immune cells in the pathobiology of AD." (PMID 31649511, 2019). "TREM2 mutations strongly increase the risk of developing Alzheimer’s disease (AD) and other neurodegenerative diseases including frontotemporal dementia (FTD), Parkinson’s disease and amyotrophic lateral sclerosis." (PMID 30630532, 2019). "Variants of triggering receptor expressed on myeloid cells 2 (TREM2) are associated with an increased incidence of Alzheimer’s disease, as well as other neurodegenerative disorders." (PMID 31101881, 2019). "Low frequency coding variants in TREM2 are associated with Alzheimer disease (AD) risk and cerebrospinal fluid (CSF) TREM2 protein levels are different between AD cases and controls." (PMID 31068200, 2019). "Genetic factors that influence Alzheimer’s disease (AD) risk include mutations in TREM2 and allelic variants of Apolipoprotein E, influencing AD pathology in the general population and in Down syndrome (DS)." (PMID 30909239, 2019). "Colonna’s lab found that in Alzheimer’s disease (AD) patients and the 5xFAD transgenic murine model, deficiency in TREM2 caused autophagy of microglia in vivo." (PMID 29887864, 2018). "Mouse models accurately reproducing phenotypes observed in Alzheimer’ disease patients carrying the R47H coding variant are required to understand the TREM2 related dysfunctions responsible for the enhanced risk for late onset Alzheimer’s disease." (PMID 30185230, 2018). "The R47H variant of Triggering Receptor Expressed on Myeloid cells 2 (TREM2) confers greatly increased risk for Alzheimer’s disease (AD), reflective of a central role for myeloid cells in neurodegeneration." (PMID 29859094, 2018). "A rare H157Y variant of TREM2 is associated with increased risk of Alzheimer’s disease; amino acid 157 is at the cleavage site for ADAM10, and H157Y is shed more readily." (PMID 30013551, 2018). "Higher mean diffusivity was associated with lower CSF amyloid-β1-42, higher CSF tau and CSF soluble TREM2, suggesting that early white matter alterations were associated with primary Alzheimer’s disease pathology and microglia activity." (PMID 30239611, 2018). "The R47H variant of the Triggering Receptor Expressed on Myeloid cells 2 (TREM2) significantly increases the risk for late onset Alzheimer’s disease." (PMID 30185230, 2018). "Rare coding variants of TREM2 (R47H, R62H) are associated with increased risk for Alzheimer's disease (AD), but how they confer this risk remains uncertain." (PMID 30341064, 2018). "In summary, our findings indicate that the Alzheimer’s disease-associated Trem2 R47H variant confers a loss of TREM2 function, impairing myeloid cell responses to pathology." (PMID 29859094, 2018). "We have previously shown CSF levels of soluble TREM2 to be increased in the prodromal at-risk state of Alzheimer’s disease, preceding the estimated age of onset of dementia symptoms by ∼5–10 years as estimated in autosomal-dominant Alzheimer’s disease." (PMID 30239611, 2018). "A missense variant of triggering receptor expressed on myeloid cells 2 (TREM2) (p.R47H) was recently shown to increase the risk of multiple NDDs, including Alzheimer’s disease and ALS in genome-wide association studies (GWAS)." (PMID 30509290, 2018).